IL17A (interleukin 17A)
Diseases named in the same sentence as IL17A in open-access papers (continued):
Sharing a sentence is not in itself a finding about the gene and the disease.
infection (continued). "In C57BL/6 mice infected with DENV, γδ T cells underwent significant expansion by day 4 post-infection and were the major producers of IL-17A in the spleen, which is negatively regulated by IL-22." (PMID 40245023, 2025). "For instance, research using immunocompetent C57BL/6 and BALB/c mice demonstrated that the resolution of infection occurred on day 16, primarily mediated by the production of IL-17A and IL-2." (PMID 41156648, 2025). "Circulating levels of TNF-α, IL-1β, and IL-17a were elevated in mice infected with fas2Δ/Δ at 24 h post-infection compared to WT, whereas IFN-γ and IL-6 levels were significantly decreased but comparable to the saline (mock infection) control." (PMID 40138332, 2025). "In this model, TNF-α signaling was the most important upstream master regulator, because its blockade completely protected mice from lethal infection and suppressed the induction of most cytokines such as IL-1β, IL-17A, IL-6, and IL-12p70." (PMID 40127923, 2025). "Infection with ESX-1 or PDIM mutants results in significantly increased Th17 T cells and IL-17A cytokine in the lungs, and infection of IL-17A deficient animals partially restores virulence of ESX-1 and PDIM mutants." (PMID 40463021, 2025). "Animals infected with the low-virulence strain 534 showed a low and stable percentage of CD3+, CD4+, and IL-17A+ lymphocytes during the first and second weeks of infection." (PMID 39024223, 2024). "Later in infection, IL-1β signaling also triggers the activation of IL-17A secreting T helper 17 (Th17) cells, modulating the Th17/T regulatory cell (Treg) balance, which will be discussed in greater detail below." (PMID 39015565, 2024). "ATF3 has been reported to facilitate the generation of IL-17A in γδ T cells through macrophage-mediated secretion of IL-1β, thus modulating the response to infection." (PMID 38255898, 2024). "LPS-induced IL17A gene expression showed contradictory results compared to the unstimulated condition, likely due to the response to infection." (PMID 39272988, 2024). "The percentage of IL-17A+ neutrophils was high during days of maximal bacterial growth control in the low-virulence strain infection." (PMID 39024223, 2024). "In IL-17RA−/− mice deficient in neutrophils with pulmonary C. neoformans (H99γ) infection, studies show that γδT-cells were the main producer of IL-17A in the lung and was further confirmed ex vivo." (PMID 39452664, 2024). "On the other hand, it was observed that vaccination with the EPS301-adjuvanted rPcrV significantly enhanced IL-17A compared with other groups in response to an infection both on day 7 and day 112 post vaccination." (PMID 39556597, 2024). "Promoting the development of type 3 immune cells after birth significantly ameliorates infection severity by enhancing IL-17A-mediated immune responses and preserving intestinal integrity." (PMID 39435479, 2024). "At 72 h post‐infection, these cytokine/chemokine levels shifted with significantly lower IFNγ and IL‐4, significantly higher IL‐5, IL‐10, IL‐17a, and CCL‐5/RANTES, and comparable IL‐2 and TNFα levels." (PMID 37990641, 2024). "Most notably, the raP group, among all groups tested, including the commercial control group, showed the highest-level stimulation for both IFN-gamma and IL-17a at 1 week post-infection." (PMID 38276680, 2024). "MPV infection at 72 hours reveals a transcriptional shift toward IL17A and genes related to cellular signaling and immune responses, implying a complex interplay between inflammation and cellular reprogramming." (PMID 39591472, 2024). "We observed that the infection significantly induced the expression of Il22 and Il17a in ILC3s, particularly in the CCR6+ cell compartments." (PMID 39013884, 2024). "In contrast, mice infected with the highly virulent 04–303 strain and treated with IL-17A blocking antibodies showed a significant decrease in survival, an increase in bacillary loads on Day 24 post-infection, and significantly more and earlier necrosis." (PMID 39024223, 2024).
infection (continued). "The ETBF-infection-induced NF-κB pathway in colonic epithelial cells has been reported to be activated by IL-17A cytokines secreted by Th17 or γδT cells." (PMID 39330861, 2024). "We found that recolonization of these mice with WT C. sporogenes, but not with the fldC mutant, restored the numbers of lung γδ T cells, and the IL-17A response after the infection." (PMID 38227652, 2024). "In these mice, neutralization of IL-17A produced a significant decrease in survival, an increase in necrosis on Day 21 and significantly higher bacilli burdens on Day 24 post-infection, in comparison with the control group that received isotype antibodies." (PMID 39024223, 2024). "Interleukin 17a (IL-17A) is the founding and most thoroughly studied member of the IL-17 cytokine family that is strongly induced in response to infection and injury, including fractures." (PMID 38612562, 2024). "In detail, levels of pro-inflammatory factors, including interleukin (IL)-6, IL-8, and IL-17A, peaked on the first day of infection and gradually declined in the subsequent days." (PMID 38765687, 2024). "In the context of the present study, pathogen-induced upregulation of il17a can potentially enhance the damage to the epithelial barrier and thus contribute to the establishment of the infection." (PMID 38601152, 2024). "Studies in mice and humans have confirmed the importance of IL-17A and its receptor IL-17RA in controlling infection and supporting IgA antibody responses." (PMID 39201314, 2024). "Some studies have shown that IL-17A is an important effector of mammary immune responses to E.coli, and local enhanced production of IL-17A can improve the outcomes of early infections." (PMID 38891619, 2024). "To assess the contribution of Vγ2+ and Vγ3−Vγ2− γδ T cells to the production of IL-17A following VACV infection, we measured transcript levels of il17a mRNA in uninfected or infected WT or TCRδ−/− mice, 5d post-infection." (PMID 38543790, 2024). "We, therefore, measured IFN-γ-secreting and IL-17A-secreting γδ T cells after infection on day 7 post vaccination in response to infection." (PMID 39556597, 2024). "IL-17A is a cytokine and a chemokine with a double-edged sword which can either protect humans from infection or make humans diseased in several clinical scenarios." (PMID 38451335, 2024). "Upon infection, the expression of Il17a increased in an age-dependent manner, leading to significantly elevated levels in P. aeruginosa-infected PCLS of old versus young mice." (PMID 38178102, 2024). "TCR−/− mice were treated with IL-17A at 24 hours post-infection (PI), and the WT mice received treatments of fingolimod (FTY720) and anti-IL-17A." (PMID 39504049, 2024). "In contrast, the IL-17A response was also highly described as a cytokine biomarker of infection and protection in the immune response to bovine TB." (PMID 39024223, 2024). "Together, these data indicated that intestinal ILC3s contributed to IL-17A levels in the periphery for host defense against infection." (PMID 39013884, 2024). "P. aeruginosa is recognized for inducing neutrophilic inflammation in airway epithelial cells, which triggers increased chemokine synthesis, including IL-8, IL-17A or IL-22, consequently leading to neutrophil recruitment to infection sites." (PMID 38790988, 2024). "Initially, the infection promotes a mixed Th1 and Th17 response with a dramatic release of pro-inflammatory cytokines, such as interferon γ (IFNγ) and IL-17A." (PMID 38343887, 2024). "RA infection causes high mortality and morbidity rates in ducks, and previous studies have indicated a role of IL-17A in the pathogenesis of infection." (PMID 38792803, 2024). "Mice infected with the high-virulence strain 04–303 showed a rapid and stable increase of CD3+, CD4+, and IL-17A+ cells from Days 3 to 14 after infection." (PMID 39024223, 2024). "On day 5 after infection, fewer colonic ILC3s from Ire1αΔRorc mice produced IL-22 and IL-17A than did ILC3s from Ire1αfl/fl mice." (PMID 38722686, 2024).
infection (continued). "FcεR1γ expression in ILC3s promotes the host defense against local C. rodentium and systemic Candida albicans (C. albicans) infections by promoting IL-17A and IL-22 secretion." (PMID 39013884, 2024). "The IL-17A, IL-17F, and IL-22-producing type 3 ILCs were significantly higher in the ace2Δ after 14 days post-infection." (PMID 39475280, 2024). "It was also shown that IL-17A and IL-17F, which are crucial for pathogen clearance, were produced immediately after infection in an IL-23-dependent manner by the ILCs present in the oral mucosa." (PMID 38391948, 2024). "On gene expression level, age-dependent differences only were observed for Tnf and Il1b of PAO1-infected lung slices and Il17a after infection with either of the two bacterial strains." (PMID 38178102, 2024). "Both mouse strains have higher levels of TNFα, IL-6, IL-17A, and IL-17F in whole stomach homogenates after infection, illustrating that the type 3 model of gastric mucosal inflammation and C. albicans pathogenesis is applicable in both C57BL/6 and BALB/c mice." (PMID 39347572, 2024). "Cattle experimentally infected with M. bovis strains show both CD4+ and CD8+ lymphocyte activation during the early stages of infection, as well as IL-17A gene expression that correlates with lung pathology." (PMID 39024223, 2024). "This process is essential for stimulating the secretion of IL-17A, which is necessary for early defense against infections and crucial to eradicating S. pneumoniae." (PMID 38255898, 2024). "The IL-17 family comprises six members (IL-17 A-17 F), which have multiple biological functions and can promote immunity to pathogens and drive inflammatory pathology during infection and autoimmunity." (PMID 38802947, 2024). "In contrast, infection with the highly virulent strain 04–303 induced a peak of IL-17A expression on Day 14 of infection, 1 week before extensive pulmonary necrosis was seen, being lymphocytes and macrophages the most important sources." (PMID 39024223, 2024). "C. albicans promotes OC via IL-17A/IL-17RA and macrophage involvement; more specifically, the infection with C. albicans increases the production of IL-17A by Th17 cells." (PMID 39272855, 2024). "IL-17A-producing CD4 Th17 cell-dependent immunity is important for protection against infections with single Sp infection." (PMID 37222516, 2023). "Despite this decrease of inflammatory markers, at 72 h post-infection, a remarkable increase of cytokine expression (IL-17A, IL-6, IL-1β and IL-8) was detected." (PMID 37047702, 2023). "Based on punctate fluorescence, expression of IL-17A (488 nm) at the protein level was the highest at 21 days post infection (dpi) in vvMDV-RB1B-infected chicken when compared to 4 and 10 dpi." (PMID 37631976, 2023). "Type 17 immunity plays an important role in controlling infection by extracellular bacterial pathogens, including Sp, through IL-17A production." (PMID 37222516, 2023). "The results also demonstrated that M220+CQ affected the profile of Th cells during infection by increasing IL-10- and IL-17A-positive cells and Treg lymphocytes." (PMID 38256880, 2023). "We observed relatively lower mRNA expression of inflammatory cytokines (IFN-γ, TNF-α, IL-4, IL-6, IL-17A and IL-33) in BA.5 infection as compared to ancestral Wuhan-Hu-1 infection." (PMID 37704701, 2023). "IL-17A in T. gondii infection plays a role in the recruitment of neutrophils to the sites of infections." (PMID 37719029, 2023). "HVT vaccination and/or pre-treatment with the rchIL-17A or empty vector followed by infection with vvMDV-RB1B resulted in an increase in IL-17A transcript levels." (PMID 37631976, 2023). "Experimental infection with the same ETEC H10407 strain has also been shown to induce significantly increased levels of IL-17A and IFN-γ in serum of volunteers who developed symptomatic infection." (PMID 37809062, 2023).
infection (continued). "Previous studies in Yang lab have shown that γδ T cells are the major producers of IL-17A at the initial stage of infection and quickly return to the background level at day 4 post-infection." (PMID 36902294, 2023). "IL-17A enhances the migration of neutrophils to the site of infection as well as their phagocytic activity and promotes the eradication of intracellular bacteria like Chlamydia muridarum by increasing the activity of the inducible nitric oxide synthase." (PMID 38567057, 2023). "In contrast to ST4 colonized mice, infection with ST7 markedly increased the percentage of pro-inflammatory cytokines IL-17A and TNF-α-producing T cells in the colonic lamina propria (LP)." (PMID 36793854, 2023). "Neutralizing anti-IL-17A during PR 8 infection reduces intestinal injury, suggesting that PR 8 infection influences intestinal microbiota composition and promotes Th17 cell mediated intestinal injury." (PMID 37233297, 2023). "This non-traditional Treg cell secretes pro-inflammatory factors (e.g.IL-17A) under inflammatory conditions (e.g.IL-6/IL-23/IL-1β/TLR stimulation) that exacerbate severe damage during infection instead." (PMID 37275865, 2023). "When the maximum levels of IL-17A responses at any time point of infection were analyzed, increased IL-17A responses were found against both dmLT (56%) and LTB (45%)." (PMID 37809062, 2023). "Infected female Il17af−/− mice also gained weight during infection (~8–19%) in a similar pattern to C57BL/6 females, although similarly to males, IL-17A/F-deficient females gained more weight than their C57BL/6 counterparts." (PMID 37923768, 2023). "By contrast, primary infection of goats was identified with a rise of SOX4/IL-17A and γδ T cell receptor transcripts, highlighting a different role for γδ T cell subpopulations during vaccination and infection." (PMID 36788233, 2023). "IL-17A and IL-17F evolved to protect against infection via the regulation of protective responses against infections at mucosal and epithelial surfaces, including the intestines, skin, lungs, and oral cavity." (PMID 37373452, 2023). "We observed that at 7 days post-infection, there was a significant expansion of IL-17A+ cells, including TH17 (CD45+, CD3ε+, CD4+, GFP+) cells." (PMID 37923768, 2023). "Our results so far indicate that chronic iWAT infection leads to an expansion of local IL-17A-producing Teff cells." (PMID 37923768, 2023). "The transcript levels of all the cytokines tested were significantly increased in old Hap-I mice as compared to adult Hap-I (except il-17a) as well as their Hap-II counterparts on day five post-infection (Figures 4A1–A4)." (PMID 37266014, 2023). "To validate the in silico prediction that there is an expansion of IL-17A+ cells in the murine iWAT in response to infection, we next measured IL-17A expression using a murine reporter line, in which IL-17A expression is coupled to GFP expression (IL-17AGFP)." (PMID 37923768, 2023). "Expression of both IL-17A and IL-17F was downregulated at 4 hours post-infection in both RNA-seq and qRT-PCR analyses, displaying minimal variation." (PMID 37930983, 2023). "Gammaherpesviruses, such as murine gammaherpesvirus 68 (MHV68), preferentially modulate the mouse immune system following primary infection, leading to IL-17A expression." (PMID 37631976, 2023). "CD8+ T cell was reported to be increased in RSV severe infection group accompanied by the decrease of IL-17A compared to the moderate infection group." (PMID 36793128, 2023). "The vaccine without PHAD (J8-Lipo-DT), whilst protective cannot rely on cellular immune mechanisms involving IL-17A or IL-2, which significantly protect the host from infection." (PMID 37749129, 2023). "In hyper-susceptible I/St mice, B-cell content markedly drops between weeks 12–16 post-infection, paralleled by diffuse lung tissue inflammation and elevated gene expression levels for pro-inflammatory cytokines IL-1, IL-11, IL-17a, and TNF-α." (PMID 36674664, 2023).
infection (continued). "Most IL-17A produced in the early phase of ETBF infection response was reported to depend on Th17 cells, and the late stage of the ETBF-induced inflammatory response was reported to depend on γδ T cells." (PMID 38203534, 2023). "Treatment with an anti-IL-17A Ab protected 50% of mice from lethal infection, although their body weight decreased." (PMID 37939119, 2023). "Infection with some HPV types (i.e., high-risk HPV-35, -39, and -68) was associated with higher cervicovaginal cytokine concentrations, particularly of IL-17A, IL-17F, TNF-α, IL-25 and IFN-γ." (PMID 36992467, 2023). "Contrary to the rapid induction in immunocompetent C57BL/6 mice after SC5314 infection, IL-17A RNA expression was almost undetectable in immunodeficient Rag2γc mice due to the lack of IL-17A-producing lymphoid cells." (PMID 38298919, 2023). "We detect expansion of dermal IL-17A-producing Vγ6+ cells during infection, which occurs in the subcutaneous adipose tissue." (PMID 37644007, 2023). "At 24 hours post-infection, IL-17A expression was upregulated across both methods, while IL-17F expression was upregulated in RNA-seq and downregulated in qRT-PCR, displaying minimal variation." (PMID 37930983, 2023). "IL-17A-producing γδ T cells can be considered as a separate cell type, and they play a crucial role in host defense against infections such as bacteria, fungi, and viruses." (PMID 37475963, 2023). "IL‐17A is a crucial factor for pulmonary protection, contributing significantly to the defense against infections and the preservation of epithelial cell homeostasis." (PMID 37249293, 2023). "This was unexpected, as both TNF-α and IL-17A/F drive host defense against S. aureus at other infection sites (e.g., skin and orthopedic implants)." (PMID 37483624, 2023). "On day 7 post-infection both PD-1 and IL-17A demonstrated higher scores in the intestine of diabetic-untreated mice compared with non-diabetics and healthy control; whereas, claudin-1 revealed worsening expression." (PMID 37719029, 2023). "Other pathways enriched in the data from 6 hours post infection include the extrinsic prothrombin activation, signaling by Rho GTPases, IL-17A signaling in gastric cells, and IL-8 signaling pathways." (PMID 37615437, 2023). "Our data shows that, as compared to ancestral Wuhan-Hu-1 strain, BA.5 infection in hACE2.Tg mice shows an overall decrease in the mRNA expression of IL-4, IL-6, IL-17A, and IL-33." (PMID 37704701, 2023). "Using flow cytometry, we found that the infection-driven IL-33 produced by EpCAM+CD45− cells was significantly reduced in Il17a-KO mice compared to WT controls." (PMID 37783278, 2023). "LPS stimulated IL-12, IL-17A, IL-1β, IL-6 and IL-8 were significantly higher post-infection than during antibiotic therapy, as well as Poly:IC stimulated IFN-γ, IL-1β and IL-6." (PMID 35360000, 2022). "The IFN-γ, T-bet, RORα, and IL17A genes were up-regulated and peaked at 6 h (p < 0.05) after infection and immunization, then declined and then rose again at 48 h." (PMID 36363767, 2022). "We demonstrated that excessive IL-17A production during the first 2 weeks of infection leads to increased bacterial growth, fibrotic lung damage, and mortality in the chronic phase of infection." (PMID 35363832, 2022). "A lower percentage TNF-α and a higher percentage of IL-17A of Vδ2 subset were observed in HIV/TB group than that in HIV mono-infection." (PMID 36619740, 2022). "In the current study, we reported that, as an essential pro-inflammatory cytokine, IL-17A was significantly increased in mouse brains after meningitic E. coli PCN033 infection." (PMID 35221923, 2022). "Infection with HN878 thus leads to a potent induction of IL-17A, suggesting that the extent of IL-17A-mediated anti-mycobacterial protection correlates with an overproduction of the cytokine." (PMID 36139450, 2022). "Here, IL-17A production was evident in parasite antigen-stimulated leukocyte cells obtained from immunized mice prior or after infection." (PMID 35746533, 2022).